BRD4 (bromodomain containing 4)
Diseases named in the same sentence as BRD4 in open-access papers (continued):
Sharing a sentence is not in itself a finding about the gene and the disease.
triple-negative breast carcinoma (34 papers, 2017 to 2025). An invasive breast carcinoma which is negative for expression of estrogen receptor (ER), progesterone receptor (PR), and human epidermal growth factor receptor 2 (HER2). "For instance, BRD4 was required for IL-6-stimulated and Notch1-induced cancer migration in a triple-negative breast cancer model, indicating that BRD4 linked microenvironment inflammation to cancer propagation." (PMID 36627707, 2023). "For example, BET inhibitor resistance is associated with increased BRD4 phosphorylation mediated by casein kinase 2 (CK2) in triple negative breast cancer cells." (PMID 29540837, 2018). "PCGF5 is also a component of the PRC1 (non-canonical PRC1) complex: overall, PRC1 components can interact with oestrogen receptor alpha (ERα), and the factor FOXA1 in ER-positive breast cancer cells, as well as with BRD4 in triple-negative breast cancer cells." (PMID 40867231, 2025). "In drug-resistant triple-negative breast cancer cells, decreased PP2A activity causes hyperphosphorylation of BRD4." (PMID 38381246, 2024). "In contrast, BRD4 is overexpressed in various cancers including triple-negative breast cancer where it promotes oncogenesis largely, though not exclusively through MYC family members." (PMID 38191874, 2024). "CK2 phosphorylation of BRD4 regulates BRD4 interaction with chromatin and hyper-phosphorylation of BRD4 by CK2 is linked to progression of triple-negative breast cancer." (PMID 37712702, 2023). "Our aim was to evaluate for the first time the clinical impact of BRD4 phosphorylation in triple negative breast cancer patients and as well as its potential linking with the PP2A activation status in this disease." (PMID 33809005, 2021). "The use of BRD4 inhibitors has emerged as a novel therapeutic approach in a wide variety of tumors including the triple negative breast cancer." (PMID 33809005, 2021). "Phosphorylation by casein kinase II (CK2) regulates BRD4 function, is necessary for active transcription and is involved in resistance to BRD4 drug inhibition in triple-negative breast cancer." (PMID 34754068, 2021). "It is also known that BRD2 promotes EMT, while BRD3 and BRD4 negatively regulate this process in triple-negative breast cancer." (PMID 32961679, 2020). "The hyperphosphorylation of BRD4 is also promoting BETIs resistance in triple-negative breast cancer (TNBC)." (PMID 32340605, 2020). "For instance, inhibition of BRD4 overcomes resistance to MEK inhibitors in triple negative breast cancer." (PMID 29050361, 2017). "For instance, BRD4 hyperphosphorylation and not overexpression has been associated with adverse prognosis in triple negative breast cancer." (PMID 38893083, 2024). "Furthermore, MS645 is a bivalent BRD4 inhibitor that suppresses the proliferation of triple-negative breast cancer cells by blocking the binding of BRD4 to MED1 and YY1 transcription factors." (PMID 38225241, 2024). "In addition, hyperphosphorylation of BRD4 has been identified as a resistance mechanism in triple-negative breast cancer against BET inhibition due to an increased p-BRD4-mediated recruitment of the Mediator complex, a multi-protein activator of RNA pol II28." (PMID 34754068, 2021). "Indeed, BRD4 inhibitor has been proved to significantly suppress proliferation and promoted apoptosis in many tumours, including triple-negative breast cancer." (PMID 32771023, 2020).
triple-negative breast carcinoma (continued). "In triple negative breast cancer (TNBC), hyperphosphorylated BRD4 has been shown to bind more strongly to MED1, facilitating bromodomain-independent chromatin localization." (PMID 33712563, 2021). "The BRD4 degrader MZ1 potently and rapidly induces preferential removal of BRD4 over BRD2 and BRD3, and has shown high efficacy in ovarian and triple-negative breast cancer in vivo." (PMID 33958721, 2021). "BRD4 has also been proven to be a necessary co-activator of the inflammatory transcription process driven by the combination of NF-κB with acetylated RelA, and a necessary co-activator of the diacetylated form of TWIST in triple negative breast cancer." (PMID 37446009, 2023). "First, we investigated the expression of BRD4 in different subtypes of BRCA cell lines using the Cancer Cell Line Encyclopedia (CCLE) database and found that the expression of BRD4 is higher in triple-negative breast cancer (TNBC) cell lines than in cell lines of the luminal and HER-2 subtypes." (PMID 30988278, 2019). "However, triple-negative breast cancer (TNBC), the most aggressive subtype, is not commonly associated with BRD4/MYC regulation." (PMID 31758045, 2019).
hepatocellular carcinoma (30 papers, 2016 to 2025). A malignant tumor that arises from hepatocytes. "One indication of additional activity of DDX55 was from a recent study that implicated direct interaction between DDX55 and BRD4 as upregulating β-catenin signaling in hepatocellular carcinoma." (PMID 40654921, 2025). "In hepatocellular carcinoma, silencing BRD4 or MED1 repressed the transcription of SE-associated genes like SPHK1, E2F2, CCND1, MYCN, and MYC." (PMID 38443991, 2024). "BRD4’s upregulation has been associated with EMT in hepatocellular carcinoma and in salivary adenoid cystic carcinoma." (PMID 35143483, 2022). "Mechanistically, a previous study demonstrated that BRD4 regulated MMP-9 expression through the SHH signaling pathway in hepatocellular carcinoma cells." (PMID 34421353, 2021). "BRD4 was overexpressed in three different large cohort of hepatocellular carcinoma (HCC) patients as well as in liver cancer cell lines." (PMID 27081696, 2016). "For example, BRD4 was shown to promote the growth and proliferation of hepatocarcinoma cells, enhance their ability to invade distant organs, and facilitate epithelial-mesenchymal transition in hepatocellular carcinoma." (PMID 28415703, 2017). "In this study, we investigated whether BRD4 could be a target for treatment of human hepatocellular carcinoma (HCC)." (PMID 26575167, 2016). "The epigenetic reader, bromodomain-containing 4 (BRD4), is overexpressed in hepatocellular carcinoma (HCC), and BRD4 inhibition is considered as a new therapeutic approach." (PMID 35546353, 2022). "BRD4 has been validated as a therapeutic target in many malignant tumors, including hepatocellular carcinoma (HCC), leukaemia, osteosarcoma, pancreatic cancer and so on." (PMID 28545522, 2017). "Furthermore, previous studies demonstrated that the knockdown of BRD4 could decrease the expression level of MMP9 protein, thereby restraining the migratory and invasive abilities of squamous cell carcinoma and hepatocellular carcinoma." (PMID 31621555, 2020). "To determine the clinical value of targeting CHK1 and BRD4 in MYC‐driven HCC, we assessed the role of CHEK1 and BRD4 expression in the pathogenesis of HCC in patients from the Genomic Data Commons (GDC) The Cancer Genome Atlas Liver Hepatocellular Carcinoma (TCGA‐LIHC) data set." (PMID 36684069, 2023).
glioblastoma (29 papers, 2015 to 2026). The most malignant astrocytic tumor (WHO grade IV). "Intriguingly, the D463H binder BRD4 has been implicated as an oncogenic regulator of many cancers, including glioblastoma, and is widely linked with Myc-driven tumorigenesis." (PMID 41187221, 2025). "Brd4 has been shown to associate with NF-κB on the promoter of BIRC5 (gene for Survivin) to facilitate mRNA expression of Survivin in glioblastoma cells with IL-6 stimulation." (PMID 36539410, 2022). "In conclusion, our results suggest that OGT and BRD4 regulate a common set of genes involved in glioblastoma proliferation, invasion, and migration but act independently in terms of their role in transcriptional regulation." (PMID 37689115, 2023). "Numerous studies in the past have shown BRD4 to be dysregulated in various types of cancers including glioblastoma, and BRD4 inhibitors are already in clinical trials as glioblastoma therapy." (PMID 37689115, 2023). "In glioblastoma stem cells isolated from PDX mouse models originally derived from human tumor samples, a subset of super-enhancers at the loci of critical genes, such as CDK6, SOX2, EGFR and BRD4, are shared by the majority of human glioblastoma stem cells." (PMID 38135679, 2023). "This provides yet another reason for the combined use of CDK9 and BRD4 inhibitors to synergistically inhibit proliferation of glioblastoma cells." (PMID 34207158, 2021). "BET proteins are also required for glioblastoma cell proliferation, mRNA of BRD2 and BRD4 are significantly overexpressed in glioblastoma, while disruption of BRD4 expression reduced glioblastoma cell cycle progression." (PMID 25849938, 2015). "At the same time, simultaneous nanoparticle-mediated delivery of temozolomide, and OTX015, an epigenetic inhibitor of bromodomain-containing protein 4 (BRD4), can block the tumor expression of PD-L1 and make glioblastoma cells a target for chemotherapy and immunotherapy." (PMID 39408784, 2024). "Finally, we found that chemical inhibition of BRD4 potentiated the effects of OGT inhibition in reducing glioblastoma cell proliferation, invasion, and migration." (PMID 37689115, 2023). "Based on these evidences, we hypothesized that BRD4 could be O-GlcNAcylated by OGT in glioblastoma which may regulate its function in transcription regulation of target genes." (PMID 37689115, 2023). "Finally, HOTAIR is regulated by the glioblastoma proliferative pathway, specifically by bromodomain and extra-terminal domain proteins, such as bromodomain-containing 4 (BRD4), which binds to and increases HOTAIR levels in this pathway." (PMID 33980320, 2021). "Previous studies verified that BRD4 was abundantly expressed within the myocardium and it could directly bind to the Hotair promoter, thereby promoting Hotair expression in glioblastoma cells." (PMID 32256945, 2020). "We propose BRD4 and OGT act independently in the transcriptional regulation of a common set of genes and that combined inhibition of OGT and BRD4 could be utilized therapeutically for more efficient glioblastoma cell targeting than targeting of either protein alone." (PMID 37689115, 2023). "Thus, combined inhibition of OGT and BRD4 could be utilized as a therapeutic strategy for highly efficient glioblastoma targeting than either protein alone." (PMID 37689115, 2023). "Thus, we believed that combined inhibition of OGT and BRD4 may have synergetic effect on glioblastoma cells." (PMID 37689115, 2023). "Epigenetic dysregulation is increasingly recognized as a key driver of glioblastoma (GBM), with bromodomain-containing protein 4 (BRD4) emerging as a critical regulator of tumor malignancy." (PMID 41828493, 2026). "H3K9la directly activates oncogenes by recruiting bromodomain-containing protein 4 (BRD4) to enhancer regions, driving glioblastoma cell proliferation and therapy resistance." (PMID 40869269, 2025).
glioblastoma (continued). "BRD4-specific inhibitors restore sensitivity to osimertinib in resistant EGFR-mutant lung cancer, and induce autophagy-dependent differentiation in glioblastoma." (PMID 41583469, 2025). "In glioblastoma models, U87 and U251 showed that NO activates NF-κB, PI3K/Akt pathways and even proteins such as Survivin and Brd4, contributing to growth and aggressiveness." (PMID 40649317, 2025). "BET protein is also necessary for the proliferation of glioblastoma cells, BRD2 and BRD4 mRNA are significantly overexpressed in glioblastoma cells." (PMID 36711038, 2023). "BRD4, a member of the bromodomain and extraterminal (BET) subfamily of human bromodomain proteins, whose inhibitor combined with EGFR CAR-T cells suppressed the growth and metastasis of glioblastoma cells and prolonged survival in mice." (PMID 36635683, 2023). "We found BRD4 to be O-GlcNAcylated in glioblastoma cells; however, OGT knockdown/inhibition neither changed its expression nor its chromatin association on promoters." (PMID 37689115, 2023). "Brd4 inhibition abrogated an the constitutively active mutant form of the EGFR receptor (EGFRvIII)-induced transcription expression of BIRC5 and eliminated IL-6-mediated therapy resistance in glioblastoma." (PMID 36539410, 2022). "As we found the expression of BRD4 or its recruitment on OGT target genes remains unaffected due to OGT reduction, we postulated that BRD4 inhibition along with OGT reduction may have a synergistic effect on mRNA expression of target genes, thus affecting glioblastoma cells." (PMID 37689115, 2023). "Furthermore, it has been shown that BRD4 binds to the HOTAIR promoter and that treatment of glioblastoma cells with I-BET151 (an inhibitor against BRD4 and others in the bromodomain and extraterminal domain (BET) protein family) reduced levels of HOTAIR transcripts." (PMID 34207158, 2021). "Notably, an shRNA loss-of-function screen demonstrated that glioblastoma cells in an orthotopic xenograft mouse model, but not in vitro, were dependent on JMJD6 and BRD4 for survival." (PMID 34207158, 2021).
colon cancer (26 papers, 2015 to 2025). "In colon cancer, CRISPR loss-of-function screens analysis identified bromodomain and extra terminal (BET) member protein BRD4." (PMID 36672877, 2023). "Hsa-mir-377 targets ETS1 to inhibit human clear cell renal cell carcinoma 38, targets E2F3 to inhibit non-small cell lung cancer 39, and targets BRD4 to inhibit colon cancer." (PMID 36741263, 2023). "The transcript levels of four NUPs (NUP210, NUP58, NUP37, and Rae1) were higher in colon cancer tissue among BRD4-bound NUPs." (PMID 35159127, 2022). "In an in vitro experiment, the addition of BRD4 inhibitors showed a significant inhibitory effect on the growth and metastasis of colon cancer." (PMID 34876902, 2021). "Second, restoring BRD4 expression by the BRD4 (Mut) construct only partially inhibited A1874-induced anti-colon cancer cell activity." (PMID 32978368, 2020). "POU6F2‐AS2 promoted cell proliferation and drug resistance in colon cancer by regulating miR‐377/BRD4 gene." (PMID 32100443, 2020). "Together, A1874 inhibits colon cancer cell growth through both BRD4-dependent and -independent mechanisms." (PMID 32978368, 2020). "In BRD4-knockout colon cancer cells A1874 remained cytotoxic, indicating the existence of BRD4-independent mechanisms." (PMID 32978368, 2020). "In conclusion, lncRNA POU6F2‐AS2 promoted cell proliferation and drug resistance in colon cancer by regulating miR‐377/BRD4 axes." (PMID 32100443, 2020). "Because A1874 is a novel BRD4-degrading PROTAC14, we tested its effect on BRD4 signaling in colon cancer cells." (PMID 32978368, 2020). "Significantly, A1874-induced anti-colon cancer cell activity was more potent than the known BRD4 inhibitors (JQ1, CPI203, and I-BET151)." (PMID 32978368, 2020). "We then compared the anti-colon cancer cell activity of A1874 with other known BRD4-BET inhibitors, including JQ137,38, CPI20329,39, and I-BET72640–42." (PMID 32978368, 2020). "Generally, colon cancer cell lines appeared to be relatively insensitive to apoptosis induction by BRD4-targeting drugs, which corroborates recent data." (PMID 29899872, 2018). "JMJD6 has been reported to be over-expressed in oral, breast, lung, and colon cancers and plays important roles in regulation of transcription through interactions with transcription regulator BRD4, histones, U2AF65, Luc7L3, and SRSF11." (PMID 29176719, 2017). "The bromodomain and extraterminal (BET) protein bromodomain containing 4 (BRD4) is critical for colon cancer proliferation, and decreasing levels of BRD4 influence differentiation effects during BET inhibition." (PMID 28108736, 2017). "On the other hand, we observed a higher protein expression level of BRD4 in 45 colon cancer tissues, which were collected from China." (PMID 25603177, 2015). "BRD4 isoforms have been reported to be differentially expressed in breast and colon cancer." (PMID 36364277, 2022). "Among the 12 top-scoring genes whose knockdown significantly affected colon cancer proliferation, BRD4 was deemed particularly attractive to pursue, given that BRD4 small-molecule inhibitors have entered clinical trials for several hematological malignancies and few reports have studied BRD4 in CRC." (PMID 34065438, 2021). "Furthermore, mRNA and protein expression of BRD4-dependent genes, including c-Myc, Bcl-2, and cyclin D1, was significantly decreased in A1874-treated colon cancer cells." (PMID 32978368, 2020). "Third, the novel MDM2-recruiting PROTAC remained cytotoxic in the BRD4-KO colon cancer cells." (PMID 32978368, 2020).